MMP9 (matrix metallopeptidase 9)
Diseases named in the same sentence as MMP9 in open-access papers (continued):
Sharing a sentence is not in itself a finding about the gene and the disease.
atherosclerosis (continued). "Increased expression of MMP-9 was detected in human atherosclerosis, but the functional roles of MMP-9 in atherosclerosis remain unclear from mouse studies." (PMID 30413026, 2018). "NGAL modulates the enzymatic activity of matrix metalloproteinase-9 (MMP-9) and is an important mediator of plaque instability in atherosclerosis, suggesting that it might play a role in thrombo-inflammation." (PMID 30443223, 2018). "Taken together, our results show NAP9 nanoparticles, may target atherosclerosis in vivo, and reduce the downstream expression of MMP-9." (PMID 30347750, 2018). "Elastin degradation by MMP9 also generates elastin peptides, which may impact atherosclerosis and abdominal aortic aneurysms." (PMID 28257481, 2017). "Leukocytes and their products, such as MMP-9, contribute to atherosclerosis pathophysiology; however, the underlying mechanisms are not completely understood." (PMID 28166283, 2017). "The indirect connection between P2X7 and MMP9 through IL-1β indicates that A740003 could play a role in the regulation of MMP9 production aimed to atherosclerosis stabilization." (PMID 28687781, 2017). "In this study, we highlighted that LPA2 was responsible for LPA-induced NF-κB activation and MMP-9 expression in macrophages, which may provide promising target for therapeutic intervention of atherosclerosis." (PMID 28496416, 2017). "Protective effects of MMP9 on atherosclerosis have also been reported." (PMID 28257481, 2017). "Studies of a transgenic MMP9-expressing mouse model suggest that MMP9 increases collagen deposition in atherosclerosis and could thus contribute to lesion stability." (PMID 28257481, 2017). "In addition, MMP-9 levels increase in cases of cardiovascular diseases, including hypertension, atherosclerosis and myocardial infarction." (PMID 28076613, 2017). "Here, we speculate that EMMPRIN and MMP-9 would be critical therapeutic targets, suppressing the expression of them can inhibit plaque rupture or retard atherosclerosis." (PMID 28261097, 2017). "BCAR1 may be affected by coxibs via other, pleiotropic mechanisms, but – like VEGFA and MMP9 – this gene has been studied functionally in the context of atherosclerosis before." (PMID 28860667, 2017). "However, both T3 treatment groups in established atherosclerosis significantly reduced MMP-9 and MMP-12 tissue expression compared to T3-negative rabbits group suggesting its potential role in attenuating progression of plaque instability." (PMID 27799085, 2016). "Accumulating clinical and experimental evidence have shown that MMP-2 and MMP-9 content and activity are correlated with atherosclerosis development, since they could decrease basement membrane and promote SMCs migration and proliferation." (PMID 25661015, 2015). "It thus appears that activation of TLR4 is fundamental for atherosclerosis due to its participation in the production of inflammatory cytokines and MMP-9, although other signaling pathways may also be involved." (PMID 25757594, 2015). "Furthermore, several matrix metalloproteinases have been reported to play roles in atherosclerosis such as MMP-9." (PMID 25830298, 2015). "Previous studies have suggested that MMP-9 is the key factor in the induction of plaque rupture, and its expression strongly correlates with lesional instability and the clinical manifestations of atherosclerosis." (PMID 26622476, 2015). "Among MMPs, MMP-9, which is induced in response to many stimulants, may specifically contribute to the pathogenesis of atherosclerosis by facilitating migration of VSMCs." (PMID 25651915, 2015). "Furthermore, the expression of MMP-2 and MMP-9 in monocytes is particularly important in penetrating the first basement membrane barrier of the ECM in the development of atherosclerosis." (PMID 25574228, 2015). "Based on these pieces of evidence, we hypothesized that agents suppressing EMMPRIN and MMP-9 expression would be potential therapeutic agents that ameliorate the development of atherosclerosis." (PMID 25241044, 2014).
atherosclerosis (continued). "Matrix metalloproteinase (MMP)-9 may play a central role in the development and progression of atherosclerosis." (PMID 25153995, 2014). "Base on these pieces of evidence, we hypothesized that agents suppressing EMMPRIN and MMP-9 expression would be potential therapeutic agents that ameliorate the development of atherosclerosis." (PMID 25241044, 2014). "MMP-9, an important member of the matrix metalloproteinase family, is involved in the invasion and metastasis of cancer cells, inflammation and angiogenesis, as well as the initiation and development of atherosclerosis." (PMID 24940407, 2014). "Although some studies have suggested the anti-atherosclerosis activity of curcumin, the mechanism by which curcumin regulates MMP-9, MMP-13 and EMMPRIN is currently unknown." (PMID 25241044, 2014). "Among this family of related proteases, MMP-1 (also called interstitial collagenase), MMP-2 (gelatinase-A), and MMP-9 (gelatinase-B) have been consistently described as significant contributors in several cardiovascular diseases including atherosclerosis, hypertension, CAD, and ACS." (PMID 23951304, 2013). "Interestingly, it was recently demonstrated that PHPT causes up- regulation of the matrix metallopeptidase 9 (MMP9) gene and a number of other inflammatory and metabolic genes in fat tissue, with possible impacts on blood pressure and atherosclerosis." (PMID 22815708, 2012). "The mechanisms linking MMP-9 expression within plaques and atherosclerosis still are speculative and maybe explained as an epiphenomenon of the increased number of macrophages within vulnerable plaques." (PMID 21457581, 2011). "Recent studies indicated that MMP-9 played an important role in the development of atherosclerosis." (PMID 20137092, 2010). "It has also been reported that gelatinase B (also known as MMP-9), an endopeptidase capable of degrading the molecular components of the extracellular matrix, is associated with increased risk for abdominal aortic aneurysm, atherosclerosis and plaque rupture." (PMID 21143924, 2010). "In addition, future studies can further screen for potential biomarkers closely associated with cardiovascular status, atherosclerosis progression, and aneurysm pathogenesis, such as the matrix metalloproteinase family (MMPs, including MMP-2, MMP-9), which mediate extracellular matrix remodeling." (PMID 40697999, 2025). "The mechanism of action of kaempferol in treating OP may involve up-regulating the expression of AKT1 and down-regulating the expression of MMP9, while participating in the Atherosclerosis-related signaling pathways, AGE/RAGE signaling pathway, and TNF signaling pathway." (PMID 38528143, 2024). "MMP-9−/− null mice studies demonstrated that MMP-9 plays a role in modulating cholesterol metabolism, suggesting that dysregulation of this system may cause metabolic disorder, atherosclerosis, and coronary heart disease." (PMID 39408801, 2024). "MMP-9 is involved in all stages of atherosclerosis and thus may contribute to CAD emergence." (PMID 35449607, 2022). "Some studies exploring the pathogenic molecular mechanisms of NGAL in atherosclerosis and CAD have shown that the NGAL/MMP-9 complexes destabilize the artery plaque, which could be detected in lipid centers and on the side facing the lumen area detected in clinical plaques." (PMID 36397150, 2022). "Similarly, the extent of atherosclerosis of other aorta sites, including AA, TA, abdominal aorta, and brachiocephalic artery, were evaluated by H&E staining, Masson's trichrome staining, and IHC (MMP-9, CTSK, CD68, and α-SMA)." (PMID 35673565, 2022). "MMP‐9 is a 92‐kDa protein that belongs to a family of zinc‐ and calcium‐dependent endopeptidases and plays a key role in all stages of atherosclerosis through monocyte recruitment influence, ECM degradation, endothelial cell migration, and activation of vascular smooth muscle cells." (PMID 34984852, 2022).
atherosclerosis (continued). "Therefore, it has been proposed that the dysregulation of MMP-9 can contribute to the development of metabolic disorders that could, ultimately, lead to atherosclerosis and coronary heart disease." (PMID 32454796, 2020). "This difference in effect may be due to the difference in substrates between MMPs; MMP-9 disrupts the basement membrane collagen, initiating the development of atherosclerosis, while MMP-12 mainly degrades the elastic laminae of atherosclerotic media without affecting plaque growth." (PMID 33082709, 2020). "Additionally, MMP2 and MMP9 (also known as gelatinase A and gelatinase B, respectively) were found to be constitutively overexpressed in models of chronic VO as well as in models of atherosclerosis and cardiomyopathy." (PMID 32271823, 2020). "The expression of other atherogenic biomarkers such as Timp1, Mmp9, Cxcl16, and Klf5 was also similar between groups, as analyzed by real-time PCR, indicating a different mechanism operating in the MG-induced reduction of atherosclerosis development in Apoe−/− mice." (PMID 30959963, 2019). "In addition, macrophages with low LRP1 levels may contribute to the exacerbation of the inflammatory process, as it has been previously shown that macrophage LRP1 deficiency contributes to increased MMP‐9, MCP‐1 and TNF‐α secretion in atherosclerosis." (PMID 28378397, 2017). "Thus, factors that regulate the expression of MMP-2 and MMP-9 in monocytes may affect the process of atherosclerosis development." (PMID 25574228, 2015). "Also, EAH reduced the expression of lectin-like oxidized low-density lipoprotein receptor-1 (LOX-1) (27%), intracellular adhesion molecule-1 (ICAM-1) (28%) and matrix metalloproteinase-9 (MMP-9) (19%), important molecular markers in the atherosclerosis pathway." (PMID 24891839, 2014). "This is the first report to our knowledge to assess the relationship of 25(OH)D concentration with MMP-9 and IL-10 in an ESRD population, and may help to shed light on mechanisms by which vitamin D deficiency is associated with an increased risk of atherosclerosis and cardiovascular disease." (PMID 21600051, 2011). "The KEGG path view suggests that LBP, MMP9, APOB, IL6, and RAP1B are involved in lipid metabolism and atherosclerosis." (PMID 41221287, 2025). "The analysis also identified inflammation-related targets within lipid and atherosclerosis pathways, such as STAT3, MMP9, MMP1, and AKT1, emphasizing the role of chronic inflammation in atherosclerosis development." (PMID 39808649, 2025). "In a mouse model of atherosclerosis, LRP1 was shown to inhibit the expression of inflammatory mediators such as CCL2 and MMP-9." (PMID 40564911, 2025). "In a low-grade inflammation state, such as established atherosclerosis, E2 can destabilize atherosclerotic plaques by inducing molecules like MCP-1 and matrix metalloproteinases (specifically MMP-2 and MMP-9) in endothelial cells." (PMID 40564184, 2025). "SGLT2 inhibitors inhibit atherosclerosis by normalizing the expression of inflammation-related genes such as TNF-α, IL-6, ICAM-1, MMP2, and MMP9." (PMID 40869372, 2025). "PDGF-CC participates in the formation of atherosclerosis by triggering MMP-2 and MMP-9 expression and monocyte migration and invasion." (PMID 38273388, 2024). "In atherosclerosis, the expression levels of CD36, PPARG, MMP9 and SRC were upregulated, while NOB inhibited their expression." (PMID 38468335, 2024). "Previous studies have shown that high doses of crocin proportionally reduce the levels of macrophages and their inflammatory derivatives in atherosclerosis, including MCP-1, TNF-α, IL-6, MMP-2, MMP-3, and MMP-9." (PMID 38830933, 2024).
atherosclerosis (continued). "It is suggested that MMP-9 and TNF-α levels have regulatory effects on ongoing inflammation, lipid metabolism and atherosclerosis." (PMID 38357561, 2023). "ST analysis showed that IGF-1 suppressed FOS/FOSB factors and gene expression of MMP9 and CXCL14 in plaque macrophages, suggesting possible involvement of these molecules in IGF-1’s effect on atherosclerosis." (PMID 36602878, 2023). "Another study demonstrated that the levels of matrix metalloproteinase-9 (MMP-9), a contributor to atherosclerosis process and heart remodelling, were higher in CAD patients with lower vitamin D levels." (PMID 36882686, 2023). "It has been reported that the expression of both MMP-9 and MMP-2 is increased in HFD-fed ApoE−/− mice with the development of atherosclerosis." (PMID 37998401, 2023). "In our work, the biochemical levels of atherosclerosis markers OPN, OPG, and MMP-9 showed statistically significant differences between the study group and healthy people in the control group." (PMID 37570897, 2023). "Analysis of GSE71226 and GSE9128 expression data of atherosclerosis group revealed that VEGFA was downregulated, while MMP9 and IL-1β were upregulated." (PMID 37880698, 2023). "MMP9 and MMP12 promoted vascular smooth muscle cell proliferation via beta-catenin pathway and contributed to atherosclerosis." (PMID 37006258, 2023). "Atorvastatin inhibits atherosclerosis and NSCLC by down-regulating the expression of MMP9, MMP12, FABP4, and CD36." (PMID 37978381, 2023). "In conclusion, MMP9, MMP12, FABP4, and CD36 genes are closely related to the occurrence and development of atherosclerosis and NSCLC." (PMID 37978381, 2023). "Therefore, increased MMP-9 gene expression, serum MMP-9 and TNF-α concentration in CAD patients could have key roles in pathophysiological state of vascular injury, susceptibility to plaque formation and atherosclerosis." (PMID 38357561, 2023). "In atherosclerosis, MMPs play a dual role: in fact, some MMPs (i.e., MMP-12) are beneficial, and others (i.e., MMP-9) appear to be harmful." (PMID 36865918, 2023). "Other studies have shown that the involvement of MMPs in atherosclerosis leads to a reduction in atherosclerotic lesions when using double knockout animals for ApoE-⁄- and MMP-2-⁄-, MMP-8-⁄-, and MMP-9-⁄- and MMP-12-⁄-." (PMID 35269673, 2022). "Atherosclerosis is known to be a chronic inflammatory process in which interleukin 6 (IL-6), myeloperoxidase (MPO), matrix metalloproteinase 9 (MMP-9), and intercellular and vascular cell adhesion molecules are used as biomarkers." (PMID 35563387, 2022). "In the lipid and atherosclerosis pathway, lncRNA AC001611.2 expression correlated positively with four genes (MMP3, MMP9, IL-1 and CXCL3) whereas six other lncRNAs correlated negatively with the same genes." (PMID 35224318, 2022). "In atherosclerosis, MMP2 and MMP9 are known to be overexpressed and act as key regulators of ECM remodeling." (PMID 35680971, 2022). "In reports regarding the pathogenesis of atherosclerosis, CD147 had been demonstrated to mediate MMP‐9 induction through ERK and the nuclear translocation of NF‐κB pathway in macrophage." (PMID 33900049, 2021). "As an upstream regulator of MMP-9, EMMPRIN is also closely correlated with the progression of atherosclerosis." (PMID 33959010, 2021). "Regarding LINC00657 (NORAD), our results are in line with a study which found that LINC00657, which is expressed in vascular endothelial cells, induced angiogenesis during atherosclerosis through the upregulation of VEGF, MMP-2, and MMP-9." (PMID 35237654, 2021). "The inflammatory cytokines and growth factors released at tissue damage sites lead to the enhancement of the expression of MMP-9 and among which TNF-α is found to be a potent stimulator of MMP-9 transcription and atherosclerosis." (PMID 33747350, 2021).
atherosclerosis (continued). "With a particular focus on atherosclerosis imaging, we highlight recent approaches to report on the activity of cathepsins (K and B), matrix metalloproteinases (MMP-2 and MMP-9), thrombin, heme oxygenase-1 (HO-1) and myeloperoxidase (MPO)." (PMID 34605500, 2021). "The present work thus aimed to study Matrix Metalloproteinase 9 (MMP-9), as a proposed link between atherosclerosis and osteoporosis in high fat diet fed rats." (PMID 33571214, 2021). "have highlighted a role of ginkgetin in improving atherosclerosis by reducing MMP-2 and MMP-9 and increasing levels of NO and NOS in thoracic aortas of rat52." (PMID 33854174, 2021). "Two of these—Gelatinase A and Gelatinase B, (also known as MMP-2 and MMP-9, respectively)—are directly involved in the pathogenesis of coronary thrombosis, atherosclerosis, myocardial infarction, and heart failure." (PMID 33477388, 2021). "In conclusion, this study showed that GDF-15 suppressed atherosclerosis by inhibiting lipid accumulation and decreasing the expressions of IL-6, IL-8, MCP-1, and MMP-9 in macrophages." (PMID 34539804, 2021). "The aim of this research was to assess the effect of Avn C on expression of MMP-9 on TNF-α-activated human arterial smooth-muscle cells (HASMC) and signaling involved in its anti-atherosclerosis activity." (PMID 33841150, 2021). "There were six targets in the intersection with 137 candidate therapeutic targets of XFZYD, which included upregulated PTGS2, MMP9, and BCL2L1 and downregulated JUN, VEGFA, and CXCL2 in the atherosclerosis group." (PMID 33425996, 2020). "A study on atherosclerosis found that blocking the PDGF-PDGFR signaling pathway can reduce MMP-2 and MMP-9 expression in atherosclerotic plaques in mice." (PMID 31777578, 2019). "In vascular inflammation, such as atherosclerosis, NF-κB upregulates the expression of adhesion molecules (ICAM-1and VCAM-1) and matrix-metalloproteases (MMP-2, and MMP-9), further exacerbating vascular inflammation." (PMID 31717401, 2019). "The levels of MMP-9, MMP-13, and EMMPRIN were determined by immunohistochemistry in human crossed sections of carotid endarterectomy specimens, showing extensive atherosclerosis, as shown by hematoxylin/eosin, and Masson Trichrome staining." (PMID 30347750, 2018). "Clinical studies have shown that MMP-9 levels in atherosclerosis vulnerable plaques were higher than in the nonvulnerable plaque and normal control groups, and that MMP-9 and atherosclerosis plaque vulnerability were positively correlated." (PMID 30142970, 2018). "We found increased levels of MMP-9 and MMP-13 in human endarterectomies with advanced atherosclerosis, together with significant amounts of extracellular matrix (ECM) metalloproteinase inducer EMMPRIN." (PMID 30347750, 2018). "Both MMP-9 and PAR-1 contribute to pathophysiology of atherosclerosis and their expression is enhanced in individuals affected by this disease." (PMID 28166283, 2017). "MMP-9 can cleave ECM proteins and plays an important role in atherosclerosis, hypertension, myocardial infarction, heart failure, and cardiac fibrosis." (PMID 28570599, 2017). "Monocytes/macrophages play an essential role during the various stages of atherosclerosis, including stabilization of atherosclerotic plaque, especially EMMPRIN and MMP-9 overexpression by macrophages in patient with high oxLDL." (PMID 28261097, 2017). "MMP9, a zinc-dependent matrix protease typically produced by macrophages and vascular SMCs, is an established determinant of ECM remodeling in atherosclerosis." (PMID 28319050, 2017). "MMP-9 can degrade extensive ECM substrates, including Type IV collagen, which plays a key role in the revascularization, inflammation response, and atherosclerosis progression." (PMID 27375491, 2016).